INSR (insulin receptor)
Diseases named in the same sentence as INSR in open-access papers (continued):
Sharing a sentence is not in itself a finding about the gene and the disease.
Insulin resistance (continued). "Increased levels of branched chain amino acids (especially leucine) induced by high fat were found to promote insulin resistance by activating phosphorylation of mTORC1 and S6 kinases and insulin receptor substrates S1 and S2." (PMID 34207667, 2021). "Metformin is an insulin sensitizer since it enhances signaling through the insulin receptor, leading to an improvement in insulin resistance, followed by a decrease in circulating insulin levels." (PMID 34682906, 2021). "PTPN1 is of particular interest, since it encodes PTP1B, a negative regulator of the insulin receptor signaling and the vascular endothelial growth factor A (VEGFA), contributing therefore to both insulin resistance and endothelial dysfunction." (PMID 34722683, 2021). "Reactive oxygen species can induce the inactivation of the signaling mechanism between the insulin receptor and the glucose transport system, which can lead to insulin resistance." (PMID 33928135, 2021). "Our previous studies show that SIT controls hyperglycemia and insulin resistance by activating insulin receptor and glucose transporter 4 (GLUT-4) in the adipocytes of obesity induced type 2 diabetic rats." (PMID 33917607, 2021). "From the molecular point of view, insulin resistance means disruption in the cascade insulin receptor–tyrosine kinase–GLUT4 translocation." (PMID 34068151, 2021). "JNK has been shown to promote insulin resistance by inhibiting the signal through insulin receptor/IRS-1 axis." (PMID 33435282, 2021). "Increased FAK levels were found to increase glucose uptake and insulin sensitivity through insulin receptor Glut-4 translocation and FAK deficiency was associated with increased insulin resistance and TG levels." (PMID 34092237, 2021). "For instance, type 2 diabetic patients with genetically defective insulin receptors or insulin resistance due to antibodies against the insulin receptor display remarkably high adiponectin levels." (PMID 34959666, 2021). "FFAs are present in the blood in obesity, and increase insulin resistance, glucose production, inhibit movement of glucose into muscle cells, and downregulate the expression of the insulin receptor." (PMID 34441691, 2021). "Insulin resistance (IR) is the central link in the occurrence of this disease, and the mechanism is related to abnormalities in the insulin receptor signal transduction pathway." (PMID 34743745, 2021). "It is plausible that the insulin resistance was worse in males because of the lower expression of insulin receptor substrates and ileal proteins involved in gut barrier integrity." (PMID 33445530, 2021). "Hypomagnesemia is associated with decreased insulin receptor activity by reducing the affinity of ATP to the insulin receptor, leading to increased insulin resistance." (PMID 34836340, 2021). "Previous studies have demonstrated that INSR activity is defective in the skeletal muscle of obese and diabetic humans, and liver specific INSR knockout mice exhibit severe insulin resistance and glucose intolerance." (PMID 34483915, 2021). "Insulin resistance indicates an inadequate strength of insulin signaling from the InsR downstream to the final substrates of insulin action involved in multiple metabolic and mitogenic aspects of cellular function." (PMID 33708999, 2021). "As such, constitutive insulin receptor (IR) deletion in adipocytes leads to lipodystrophy, liver steatosis, and insulin resistance." (PMID 33435513, 2021). "Previous studies have shown that whole body-IRS2 knockout mice resemble insulin receptor knockout mice, as they displayed insulin resistance, hyperglycemia, reduced β-cell mass, and decreased body weight." (PMID 34568323, 2021). "In particular, it can induce insulin resistance by a phosphorylation reduction of insulin receptor substrates or transcription inhibition." (PMID 34574191, 2021).
Insulin resistance (continued). "Insulin receptor substrate 1 (IRS1), the key kinase for glucose uptake and the target of insulin resistance, is a signaling factor downstream of the insulin receptor." (PMID 34071638, 2021). "Our previous studies show that SIT controls hyperglycemia and insulin resistance by promoting insulin signaling via activation of insulin receptor and glucose transporter 4 (GLUT 4) proteins in adipose tissues of obesity induced type-2 diabetic rats." (PMID 33917607, 2021). "Defects in the insulin receptor (INSR) gene cause various severe insulin resistance conditions, including Donohue syndrome (DS), Rabson-Mendenhall syndrome (RMS) and type A insulin resistance (type A-IR)." (PMID 33995269, 2021). "In contrast, hepatocyte-specific insulin receptor knockout (LIRKO) mice exhibited severe insulin resistance and glucose intolerance, leading to a significant increase in β-cell mass as well as the failure of insulin to suppress hepatic glucose production." (PMID 34202916, 2021). "High uric acid (UA) is demonstrated to directly inhibit insulin signaling by insulin receptor modification and induce insulin resistance." (PMID 34698101, 2021). "Insulin resistance and acquired defects in the insulin-receptor signaling pathway are common in CKD patients due to their complex metabolic abnormalities." (PMID 34540994, 2021). "Reduced hypothalamic and hepatic expression of insulin receptor substrates and ileal tight junction proteins was seen in males only, explaining their greater insulin resistance." (PMID 33445530, 2021). "One of the mechanisms involved in insulin resistance is through the modulation of insulin receptor clathrin-mediated endocytosis." (PMID 34069890, 2021). "Because insulin resistance is a central trait of type 2 DM, oleanolic acid therapy increased insulin sensitivity by boosting the expression of insulin receptor and glucose transporter proteins in HepG2 cells." (PMID 34885816, 2021). "Numerous genes are candidates for severe insulin resistance, such as INSR, BSCL2, AGPAT2, CAV1, and PTRF." (PMID 33995269, 2021). "At the cellular level, insulin resistance is described as poor insulin signaling strength from insulin receptor downstream to the end substrate of the cascade." (PMID 33953863, 2021). "The inhibition of the downstream signaling of the insulin receptor is a critical mechanism by which inflammatory signaling leads to insulin resistance." (PMID 33430045, 2021). "A homogeneous polysaccharide galactose (GXG) purified from D. huoshanense promotes IRS-1 tyrosine phosphorylation in the liver of T2DM mice, restoring INSR function and improving insulin resistance." (PMID 35155528, 2021). "SOCS6 was first described to inhibit insulin receptor, which mediates cytokine-induced insulin resistance." (PMID 33712005, 2021). "Insulin resistance is a key driver of type 2 diabetes mellitus and is characterized by defective insulin receptor signaling." (PMID 34603025, 2021). "In the combined phenotype, neonates maintained on 20% or 30% fat diets had higher body weights with elevated glycemia in the former, which with the increased insulin receptor immunoreactivity reflect early events in the pathogenesis insulin resistance." (PMID 35069436, 2021). "TNF-α is an important mediator for insulin resistance in obese subjects, and it mainly induces insulin resistance by weakening the insulin receptor signal transduction." (PMID 34574191, 2021). "Computational docking analysis disclosed the possible stabilizing effect of PFOA on the complex between InsR and GM3 ganglioside, previously shown to be associated with the low grade chronic inflammation-related insulin resistance." (PMID 34539566, 2021). "In our previous study, high maternal estradiol led to insulin resistance and disordered eating in mouse offspring due to decreased insulin receptor and elevated neuropeptide Y expression in the hypothalamus." (PMID 34239542, 2021).
Insulin resistance (continued). "The pulsatility pattern likely reduces the risk of negative consequences from potentially downregulating insulin receptors (INSR), which would result in further insulin resistance." (PMID 34356863, 2021). "The modulation of insulin receptor signaling in different steps of the intracellular pathway can augment the response to insulin in several types of tissues and subsequently reduce insulin resistance." (PMID 33925692, 2021). "The protein kinase C-ε (PKCε) activated by DAG can directly inhibit INSR function, which in turn triggers insulin resistance." (PMID 35155528, 2021). "Obesity, as expected, induced insulin resistance in the adipose tissue, seen by a decreased insulin receptor, Glut4 transporter, and PPARγ levels within the visceral adipose tissue, effects not modified when obese animals were exposed to CIH." (PMID 34439481, 2021). "The pro-inflammatory properties of fetuin-A exert a direct effect on the insulin receptor, thereby supporting insulin resistance." (PMID 34768942, 2021). "Hepatic insulin resistance is aggravated by inhibition of physiological phosphorylation of the insulin receptor via the DAG–PKCε pathway and downregulation of hepatic Irs2 expression via hyperinsulinemia." (PMID 33923817, 2021). "An investigation using an animal model demonstrated that oral intake of AGEs impaired insulin uptake and induced insulin resistance by altering insulin receptor signal transduction." (PMID 33148181, 2020). "DGs promote insulin resistance in skeletal muscle by recruiting protein kinase C isoforms to the plasma membrane, which phosphorylate and inactivate the insulin receptor." (PMID 32041341, 2020). "Several parameter values were affected by the INSR genotype, particularly W/H ratio, lipid, insulin and glucose levels and insulin resistance in PCOS patients." (PMID 33033446, 2020). "Mice deficient in IRS1 by targeted disruption display insulin resistance and impaired glucose tolerance and mice heterozygous for defects in genes for both IRS1 and the insulin receptor or IRS1 and glucokinase develop overt diabetes." (PMID 32411229, 2020). "Since galectin-3 interaction with the insulin receptor has been identified as a mechanism of insulin resistance, these findings support an additional mechanism by which carrageenan exposure can impair insulin signaling." (PMID 32377523, 2020). "PCOS susceptibility variants in THADA and INSR are associated with metabolic syndrome and variants in TOX3 and DENND1A are associated with insulin resistance." (PMID 32425888, 2020). "Type B insulin resistance syndrome (TBIR) is characterised by the rapid onset of severe insulin resistance due to circulating anti-insulin receptor antibodies (AIRAs)." (PMID 32755965, 2020). "Indirectly, this theory is supported by dramatically reduced Insulin receptor transcripts and increased transcription of Insulin-like growth factor 1 (IGF-1) in CXCR5-deficient RPE cells suggestive of insulin resistance." (PMID 32492870, 2020). "Elevated hepatic GLUT2 can be observed following HFD feeding that can increase FFA synthesis blockage of the insulin receptor cascade and finally insulin resistance." (PMID 33076522, 2020). "Adiponectin level >7 mg/L in subjects with symptoms of severe insulin resistance had a 97% positive predictive value for defects of insulin receptor function." (PMID 32755965, 2020). "The reduction in insulin receptor density within the expanded adipose tissue and the subsequent development of insulin resistance both promote the uncontrollable release of FA, leading to aberrant lipid accumulation and lipotoxicity in peripheral tissues." (PMID 33193730, 2020). "Previous studies demonstrated that CAV1 is critical for insulin receptor-mediated signaling, insulin secretion, and potentially the development of insulin resistance." (PMID 32082483, 2020). "These mice have endothelial cell-specific insulin resistance due to the expression of a dominant negative human insulin receptor." (PMID 32401607, 2020).
Insulin resistance (continued). "For example, it has been shown that increased mitochondrial ROS production inhibits binding of insulin receptor substrate‐1 to the insulin receptor, resulting in insulin resistance." (PMID 31965758, 2020). "Insulin resistance then occurs via insulin receptor desensitization and downregulation due to chronic hyperinsulinemia." (PMID 32092909, 2020). "Attention has been paid to insulin resistance as the key relevant pathosis, particularly insulin receptor signaling." (PMID 33178037, 2020). "Previously, galectin-3 was shown to bind less to chondroitin 4-sulfate when ARSB was reduced, and to bind with the insulin receptor and contribute to insulin resistance." (PMID 32377523, 2020). "miR-26a ameliorated insulin resistance and enhanced bone quality, which depended on insulin receptor/signaling in osteoblast." (PMID 32278305, 2020). "The microRNA-15b binds the 3′ untranslated region of the insulin receptor mRNA preventing its translation and enhances its degradation which eventually leads to impairment in the insulin action i.e. insulin resistance." (PMID 32988370, 2020). "PSO improved hepatic insulin resistance and increased insulin receptor phosphorylation via increased proteins regulating glucose homeostasis, e.g., p-AMPK, p-AKT, p-IR-tyr972, and p-IR-tyr1146." (PMID 32751794, 2020). "Chronic activation of mTOR-C1 can lead to insulin resistance by inhibition of the phosphorylation of insulin receptor substrates." (PMID 32548072, 2020). "The primary aim was to identify known and novel INSR interactors and the secondary aims were to: 1) examine novel interactors in the context of palmitate-induced insulin resistance and 2) relate INSR interactor pathways to podocyte morphology and function." (PMID 33458251, 2020). "In this regard, MMP-8 can proteolytically modify insulin-receptor leading potentially to development of insulin resistance." (PMID 33375174, 2020). "Magnesium supplementation enhanced insulin sensitivity and decreased insulin resistance in diabetic rats mainly through increasing insulin receptor expression, affinity, and augmenting insulin receptor signaling." (PMID 32952944, 2020). "TNF has the ability to lower insulin receptor expression that contributes to the development of insulin resistance." (PMID 33363197, 2020). "A functional insulin receptor (INSR) is crucial for eliciting the intracellular molecular effects of insulin and INSR mutations lead to genetically severe insulin resistance." (PMID 32018348, 2020). "Insulin receptor (IR) and IR-related signaling defects have been shown to trigger insulin-resistance in insulin-dependent cells and ultimately to give rise to type 2 diabetes in mammalian organisms." (PMID 33266015, 2020). "BMAL1 knockdown induces insulin resistance, as indicated by markedly impaired insulin-stimulated phosphorylation of insulin receptor and AKT pathway." (PMID 32334629, 2020). "Induction of ER stress results in the suppression of insulin receptor signaling linking ER stress to insulin resistance." (PMID 32525804, 2020). "Metformin increases the expression of insulin receptor and activates tyrosine kinase, and therefore improves insulin resistance." (PMID 33664665, 2020). "In livers of FFC + E- and FFC + B-fed mice, expressions of insulin receptor (Insr) and insulin receptor substrate 2 (Irs2), shown to be indicative of hepatic insulin resistance, were significantly higher than in those of C-D-fed mice (P ≤ 0.05)." (PMID 30879098, 2020). "Clinical evidence of severe insulin resistance was corroborated by euglycaemic hyperinsulinaemic clamp, and anti-insulin receptor autoantibodies were confirmed by immunoprecipitation assay." (PMID 32755965, 2020). "Of relevance, insulin resistance at receptor levels are traced to defects in the insulin receptor signaling pathway arising from metabolic derangements accompanying kidney disease such as uremia, metabolic acidosis, anemia, and inflammation." (PMID 33076282, 2020).
Insulin resistance (continued). "The development of muscle insulin resistance has been observed in genetic mouse models of selective muscle insulin resistance, resulting from the muscle-specific inactivation of the insulin receptor and/or Glut4." (PMID 32178449, 2020). "Surprisingly, POMC-specific insulin receptor knock-in mice show exacerbated insulin resistance and increase HGP36." (PMID 33293550, 2020). "Metformin improves insulin resistance by increasing the expression of insulin receptor and activation of tyrosine kinase." (PMID 33693008, 2020). "As an extracellular signaling kinase, ERK can promote phosphorylation of insulin receptor substrate at Ser612, which leads to insulin resistance." (PMID 32892299, 2020). "In fact, several animal and human studies have supported the view that increased insulin levels, even in the presence of normal weight, induce insulin resistance, by producing insulin receptor desensitization." (PMID 31141900, 2019). "The role of impaired functionality of lipid rafts and caveolins has been reviewed in the development of insulin resistance, respectively, through alteration of INSR endocytosis." (PMID 31658625, 2019). "Through this review, we provide insights into the mechanistic role of INSR intracellular processes and activities in the development of insulin resistance and diabetes." (PMID 31658625, 2019). "Chronic hyperinsulinemia resulting from insulin resistance has been shown to decrease insulin-INSR complex internalization and lead to derangements of intracellular receptor trafficking and insulin degradation." (PMID 31658625, 2019). "SOCS family has been reported that inhibit transduction of insulin receptor signaling and resulting in insulin resistance." (PMID 31514311, 2019). "Recently, specific miRNAs have been indicated as possible mediators of insulin resistance in AT, such as miR-27b, which is upregulated in different in vitro and in vivo models of IR and directly suppresses INSR expression by targeting the 3’UTR of INSRs." (PMID 30754657, 2019). "Metformin improves insulin resistance by increasing insulin receptor expression and improving tyrosine kinase activity." (PMID 30705766, 2019). "One potential explanation for this is due to mTORC1 and ER stress hyperactivation, both of which are known to provoke insulin resistance by blocking the insulin receptor-AKT pathway." (PMID 31754457, 2019). "Insulin-mediated activation (phosphorylation) of insulin receptor substrate (IRS) proteins has been recognized as the major basis for linking insulin resistance to NAFLD." (PMID 30642126, 2019). "Galectin-3 binding to the insulin receptor (IR) leads to insulin resistance by inhibition of downstream signaling." (PMID 31179345, 2019). "There is direct evidence from studies involving humans with congenital insulin receptor signalling defects, that lowered mitochondrial ATP synthesis capacity can follow from insulin resistance." (PMID 31195596, 2019). "Insulin resistance, a major component in metabolic disorders, is generally viewed as a post-receptor signaling defect where INSR activities remain unimpaired." (PMID 31658625, 2019). "Upregulation and downregulation of insulin receptor expression is considered as a sign of increased and decreased insulin resistance, respectively (i.e., a decrease in insulin resistance requires less receptor number)." (PMID 31562377, 2019). "They dephosphorylate the insulin receptor and insulin receptor substrate proteins, resulting in hypothalamic insulin resistance." (PMID 30875909, 2019). "IL-6 demonstrates the effect on glucose metabolism by altering the IRS,Glut-4, and insulin receptor,which support in boosting the rate of insulin resistance." (PMID 31524015, 2019). "Chronic low-grade inflammation interferes with isletβ-cell proliferation and insulin receptor function, thus resulting in insulin resistance and compensatory hyperinsulinemia." (PMID 30881692, 2019).